TLR4 (toll like receptor 4)
Diseases named in the same sentence as TLR4 in open-access papers (continued):
Sharing a sentence is not in itself a finding about the gene and the disease.
COVID-19 (continued). "This hypothesis has been supported by other evidence demonstrating that TLR4 and its downstream signaling molecules are significantly upregulated in patients with severe COVID-19 compared to those with mild illness." (PMID 34834939, 2021). "Also, ongoing clinical trials of pulmonary surfactants in COVID-19 hold promise since they also block TLR4." (PMID 33505220, 2021). "Furthermore, TLR3 and TLR4 are specifically related by different studies as part of immune response in COVID-19 (Patra, Chandra Das & Mukherjee, 2021; Khanmohammadi & Rezaei, 2021; Kaushik, Bhandari & Kuhad, 2021)." (PMID 34909278, 2021). "The increase in systemic TLR4 agonists such as oxidized lipoproteins and phospholipids, heat shock proteins, extracellular matrix protein, and many other molecules secreted during COVID-19 can act as PAMPs for TLR4 and contribute to further damage the host brain parenchyma." (PMID 34281186, 2021). "In consequence, a therapy that targets the TLR4-dependent inflammatory response could in principle be effective against the respiratory distress and cytokine storms caused by SARS-CoV-2 in COVID-19." (PMID 34552685, 2021). "In detail, transmembrane receptor CD74 and TLR-4, -5, and -8, which were shown to be upregulated in response to neutrophil stimulation and to trigger neutrophil IL-8 production, were increased in patients with severe COVID-19." (PMID 34403366, 2021). "Furthermore, the immunocomplex formation of TIRAP with MyD88, called myddosome, that is required for TLR4 signal transduction, was significantly higher in platelets from patients with COVID-19 compared with HS." (PMID 34092777, 2021). "Contrary to TLR3, the mRNA transcription for TLR4 was higher in the COVID-19 SEVERE group." (PMID 34315957, 2021). "Interestingly, this pathway with its components, TLR4, MyD88, and NF-κB, was pronounced in the overlay of the heme KG and COVID-19 KG." (PMID 33925394, 2021). "It has been suggested that statins may lower IL-6 levels, and thus improve the prognosis of COVID-19 patients, by inhibiting Toll-like receptor 4 (TLR-4)." (PMID 33920709, 2021). "COVID-19 patients upregulate TLR-4-mediated inflammatory signaling that mimics bacterial sepsis." (PMID 34200327, 2021). "A critical immune response of the COVID-19—flu interaction might be the toll-like receptor 4 (TLR4)." (PMID 33352889, 2020). "In summary, HMGB1 may be involved in COVID-19 through at least two mechanisms: one is TLR4-mediated cytokine storm in immune cells, and the other is AGER-mediated ACE2 expression in alveolar epithelial cells." (PMID 33313438, 2020). "Moreover, TLR4 can be modulated by extracellular vesicles (EVs)-derived miRNAs in COVID-19." (PMID 41293166, 2025). "Additionally, the activation of TLRs post-COVID-19 could induce the release of the proinflammatory cytokine IL-1β, suggesting a crucial role for TLR4 in mediating the severity of COVID-19." (PMID 38287815, 2024). "Finally, it can be concluded that sTLR4and sCD14, as endogenous negative regulators of TLR4 signaling, may be disease severity markers with moderate sensitivity for patients with COVID-19." (PMID 38178206, 2024). "Taken together, these data suggest that the interaction of rSP with TLR2 and TLR4 on NK cells may have a strong impact on the immunopathology of COVID-19 and provides a clue that such receptors and/or their intracellular pathways could represent potential therapeutic targets." (PMID 38881905, 2024). "There is emerging evidence that direct activation of TLR4 in alveolar macrophages (AMΦ) by the SARS-CoV-2 spike protein may play a pivotal role in strong pro-inflammatory responses and associated acute lung injury (ALI) observed in severe COVID-19." (PMID 38034686, 2023). "Finally, SARS-CoV-2-induced myocarditis and multiple-organ injury may be due to TLR4 activation, aberrant TLR4 signaling and hyperinflammation in COVID-19 patients." (PMID 37112659, 2023). "Interestingly, TLR-4 has also had a role in long-term post-COVID-19 sequelae." (PMID 37508529, 2023).
COVID-19 (continued). "Therefore, modulation of PRRs/TLR4 by CHIs may reduce exaggeration immune response seen in patients with severe COVID-19." (PMID 37383608, 2023). "Thus, TLR4 signaling in macrophages could be a potential target for regulating excessive inflammation in COVID-19 patients." (PMID 37888066, 2023). "It is tempting to speculate that the elevated JNK, which has been demonstrated to induce TLR4-mediated apoptosis in various types of cells, and the decreased level of lymphocyte early apoptosis in severe COVID-19 patients revealed in the present study are intertwined." (PMID 35213582, 2022). "Therefore, SARS-CoV-2-induced myocarditis, ARDS and multiple-organ damage may be due to TLR4 activation, aberrant TLR4 signaling and excessive inflammation in COVID-19 patients." (PMID 36555339, 2022). "Therefore, as irisin reduces TLR4 expression levels, which could decrease patient immune responses to PAMPs and DAMPs, and maybe COVID-19 patient prognosis." (PMID 35784579, 2022). "Thus, TLR2 and TLR4 could be possible targets to prevent the severity of COVID-19 and develop therapeutic strategies for the disease." (PMID 35891270, 2022). "Hence, investigating anti-COVID agent(s) against TLR-4 and POP might help in alleviating neurological complications linked with COVID-19." (PMID 35885104, 2022). "In addition, patients with COVID-19 may develop a bacterial coinfection that releases LPS and activates the TLR4/MyD88 pathway." (PMID 35784579, 2022). "Therefore, it is likely that ORF3a-induced IL-6 and TNF-α production through NF-κB, TLR3 or TLR4 could all contribute to the severity of COVID-19." (PMID 35356515, 2022). "Hence, to investigate the potential roles of TLR4/TFEB in M. pneumoniae infection may provide a potential strategy for COVID-19." (PMID 35965629, 2022). "Thus, exploring new SARS-CoV-2 active drug candidates against TLR-4 and PREP may help to mitigate neurological manifestations associated with COVID-19." (PMID 35888166, 2022). "We therefore anticipate that hMOS, either as mixtures or as individual molecules, could prove to be useful as a mucosal signaling agent with TLR4 inhibitory activity to protect against respiratory mucosal inflammation and acute lung injury in patients with severe COVID-19." (PMID 35203555, 2022). "Prediction, structure analysis, experimental affinity, and clinical studies of patients with severe COVID-19 have indicated that some ACE2 polymorphisms have a higher affinity for protein S. During SARS-CoV-2 infection, severe inflammation favors the expression of ACE2 and TLR-4." (PMID 35062298, 2022). "Furthermore, SARS-CoV-2-induced myocarditis and multiple-organ injury may be due to TLR4 activation, aberrant TLR4 signalling, and hyperinflammation in COVID-19 patients." (PMID 33505220, 2021). "Therefore, TLR4 signaling in macrophages may be a potential target for regulating excessive inflammation in COVID-19 patients." (PMID 33644468, 2021). "This may be responsible for increased TLR4 expression and inflammation in COVID-19 patients." (PMID 33498183, 2021). "HMGB1 may interact with Toll-like receptor 4 (TLR4) and the advanced glycosylation end-product specific receptor to induce cytokine storm in immune cells and ACE2 expression in alveolar epithelial cells, further increasing COVID-19 susceptibility." (PMID 34545062, 2021). "In summary, our research indicated that patients with an unfavorable outcome presented lower TLR3 expression and enhanced expression of TLR4 which may be a compensatory mechanism that leads to a prominent inflammatory response that is characteristic of severely ill COVID-19 patients." (PMID 34315957, 2021). "Since severe COVID-19 patients show high expression of TLR4 in PBMCs, we can speculate that the activation of this receptor by LPS derived from the gut microbiota of elderly, diabetic, and hypertensive individuals would also potentiate the production of IL-6 induced by SARS-CoV-2." (PMID 34458281, 2021).
COVID-19 (continued). "Therefore, selective targeting of TLR4-spike protein interaction by designing competitive TLR4-antagonists could pave the new way to treating COVID-19." (PMID 33920709, 2021). "Therefore, TLR4 activation may be responsible for immunopathological manifestations experienced by COVID-19 due to increased TLR4 expression and circulating DAMPs." (PMID 33498183, 2021). "The first plant polymer-based TLR4 agonist, inulin acetate, which is synthesized from plant polysaccharide inulin, has been reported to induce strong systemic and mucosal immunity and may be useful in the development of a COVID-19 vaccine." (PMID 34835108, 2021). "Hence, improving excessive TLR4-mediated innate signaling may be beneficial to the treatment of COVID-19." (PMID 34696490, 2021). "Additionally, TLR4 is protective in the MHV-1 SARS respiratory model and over-activation of TLR4 by phospholipids is linked to lung damage and increased levels of IL-6 in COVID-19 patients." (PMID 33377937, 2020). "In serum samples, soluble TLR-2 and TLR-4, IL-1β, IL-4, IL-6, Il-10, IFN-α, and TNF-α levels were significantly decreased in patients with coronavirus disease-19 (COVID-19) as compared with other viruses (p < 0.05 in each)." (PMID 41766850, 2026). "In conclusion, our findings demonstrate that PMN-MDSCs are capable of producing ETs upon stimulation with PRP from COVID-19 patients or with the SARS-CoV-2 Spike protein, through TLR4-independent and TLR4-dependent mechanisms, respectively." (PMID 41322987, 2025). "Emerging evidence has suggested that TLR4 binds to SARS-CoV-2, triggering immune responses and worsening kidney damage through inflammation, dysfunction, and thrombosis, according to “COVID-19” (Cluster #6)." (PMID 40584714, 2025). "Compared with the healthy group, COVID-19 patient group displayed the significantly lower expression level of BCL2, but significantly higher expression levels of MMP9, ICAM1, and TLR4." (PMID 41411324, 2025). "Based on the Degree, MCC, Closeness, Betweenness, and MNC algorithms of the CytoHubba plug-in, six genes (FPR1, FCGR2A, TLR4, S100A12, CXCL1, and LTF) were confirmed as hub genes related to COVID-19 severe." (PMID 38674681, 2024). "After the validation set (GSE171110) analysis, only four genes, namely IL-6R, TLR4, TLR2, and IFNG, showed expression changes similar to those of the training set in COVID-19." (PMID 38165854, 2024). "GSE164805 and GSE171110 dataset validation revealed significant differences between the COVID-19 and normal controls in four core genes (feature genes), namely IL6R, TLR4, TLR2, and IFNG." (PMID 38165854, 2024). "Collectively, TLR4 seems to play a crucial role in the development and progression of SARS-CoV-2 and has the potential to be a promising therapeutic target post-COVID-19." (PMID 38287815, 2024). "Studies highlight the role of TLR2 in innate immune activation in COVID-19,98 alongside TLR1, TLR4, and TLR6, with TLR4 demonstrating the highest affinity for the virus." (PMID 39113913, 2024). "We performed a study using peripheral blood mRNA-seq data from 41 COVID-19 patients to obtain the immune-characterized genes of COVID-19 severe disease, namely, the hub genes (FPR1, FCGR2A, TLR4, S100A12, CXCL1, and LTF)." (PMID 38674681, 2024). "The new evidence suggests that in addition to the known ACE2 receptor, TLR-4, KIM-1/TIM-1, and CD147 play crucial roles in the pathogenesis of COVID-19 and specifically in the mediation of viral entry into kidney cells and the onset of kidney cell damage." (PMID 38287815, 2024). "The CSF2, IFNG, and IL1B expression levels were considerably lower in the COVID-19 than in the Healthy group, while those of IL6R, TLR2, TLR4, and TNF were higher." (PMID 38165854, 2024). "In the bulk RNA-seq discovery cohorts for both COVID-19 and AMI, WGCNA’s intersection analysis and machine learning identified TLR4 and ABCA1 as significant hub genes, demonstrating high diagnostic and predictive value in the RNA-seq validation cohort." (PMID 38022594, 2023).
COVID-19 (continued). "The percentage of methylation of the TLR4 and TNF-α promoters was significantly higher in COVID-19 patients than in healthy subjects (P = 0.003 and 0.005, respectively)." (PMID 36840831, 2023). "We investigated these genes’ expression patterns further in the validation cohort and discovered that two genes, TLR4 and ABCA1, showed statistical differences in both the COVID-19 and AMI cohorts." (PMID 38022594, 2023). "Interestingly, dexamethasone has been demonstrated to lower the 28-day mortality rate among patients hospitalized with COVID-19 receiving respiratory support, providing a clinical benefit that could also be explained by the inhibition of TLR4-mediated activation in the endothelium." (PMID 37175768, 2023). "Therefore, inhibition of TLR4 by HDMs may reduce thrombotic events in COVID-19 patients." (PMID 37383608, 2023). "Studies of innate activation unrelated to COVID-19 are also very limited, revealing TLR1, TLR2, TLR3, TLR4, TLR7 and TLR8 activation." (PMID 36769320, 2023). "The signaling network involving TLR4 and VEGFA in COVID-19 ARDS is more complex than in pneumonia and shows additional activating effects of downregulated miR-150-5p and miR-126-3p on VEGFA." (PMID 36776845, 2023). "Severe COVID-19, however, is characterized by additional activation of TLR1, TLR2, TLR4, TLR5, TLR6, NOD1 and NOD2, which are primarily responsive to bacterial antigens." (PMID 36769320, 2023). "Here, we observed that, at admission, COVID-19 patients had a low response to the agonist of TLR2, TLR4, TLR7/8, and TLR9, suggesting a TLR cross-tolerance." (PMID 37189696, 2023). "Another study reported decreased functioning of DCs from COVID-19 patients towards TLR triggers during acute SARS-CoV-2 infection as DC activation upon TLR3, TLR4, TLR7 and TLR8 triggering was suppressed." (PMID 37844099, 2023). "In the case of COVID-19, innate immunity detects SARS-CoV-2 through pattern-recognition receptors (TLR1, TLR4, and TLR6) and activates downstream cascades to initiate viral clearance." (PMID 36833234, 2023). "It is thought that the production of proinflammatory cytokines is induced by the activation of different TLRs, such as TLR2, TLR4, and TLR7/8, which greatly contributes to the pathogenesis of COVID-19 and its severity." (PMID 35832809, 2022). "Next, we further analyzed the possible binding of vitamin D with the seven COVID-19/HCC targets (HMOX1, MB, TLR4, ALB, TTR, ACTA1 and RBP4) identified previously and found that vitamin D only binds to MB and RBP4." (PMID 36275701, 2022). "Bioactive compounds in this plant target the significant COVID-19 responsible receptors such as MAPK14, ACE, TLR4, and MAPK8, which makes this plant an ideal candidate for treating this deadly infection." (PMID 36144690, 2022). "S1 cells exhibited the highest expressions of alarmins S100A8, S100A9, S100A12 and toll-like receptors TLR4 and TLR8, all of which are involved in neutrophil activation and were the most mature neutrophils in both KD and Severe COVID-19 patients." (PMID 36159873, 2022). "Parallel to the expression of MyD88, the expression of TLR1, TLR2, TLR4, TLR5, TLR8 and TLR9 was significantly elevated in patients with severe and critical COVID-19." (PMID 35682644, 2022). "In COVID-19 patients, HMGB1 can be released from dying cells and functions as a pro-inflammatory inducer to bind with TLR4, leading to the production of IL-1β, IL-6, and TNF-α." (PMID 35832809, 2022). "Using Venn diagram mapping, we further identified five core ferulic acid targets against OS and COVID-19 via autophagy, including MAPK1, TLR4, PIK3R1, STAT3, and PARP1." (PMID 36204096, 2022). "For example, in severe COVID-19, TLR7 (viral) and TLR4 (bacterial/fungal) synergize, TLR9 and TLR4 (both bacterial/fungal) synergize and TLR2 and TLR4 (both bacterial/fungal) synergize with NLRP3 (viral and bacterial)." (PMID 33672738, 2021).
COVID-19 (continued). "Moreover, activation of TLR4 on platelets whether by PAMPs (viraemia and LPS) or DAMPs induces a prothrombotic and proinflammatory state, which provides a potential explanation for the thrombotic events (such as MI) observed in COVID-19 patients." (PMID 33505220, 2021). "In addition, a possible secondary bacterial infection during the later phase of COVID-19 may result in the stabilization of HIF-1α in macrophages via the activation of toll-like receptor 4 (TLR4) and decrease in prolyl hydroxylase mRNA in severe inflammatory vascular disease." (PMID 34690793, 2021). "The fold change or relative expression of TLR-2, TLR-4, and PGRP-4 was significantly higher in COVID-19 saliva as compared to that in the control saliva." (PMID 34707585, 2021). "To examine the role of LPS on platelet activation in patients with COVID-19, we evaluated the phosphorylation of TIRAP, that is marker of TLR4 activation." (PMID 34092777, 2021). "Furthermore, S100A9 amplified the recombinant S2 protein of SARS-CoV-2-induced IL-1β mRNA expression in PBMCs in vitro, suggesting that activation of TLR4 by LPS from the gut microbiota of elderly, diabetic, and hypertensive individuals may be related to the severity of COVID-19." (PMID 34458281, 2021). "When compared to the COVID-19 MILD group, the COVID-19 SEVERE group had lower expression of TLR3 and overexpression of TLR4." (PMID 34315957, 2021). "After comparing the collected genes, 460 host factors common to COVID-19 and dengue were found, including MMP2, PDF, PFKP, SLC25A3, IGF1, CCL4, TLR4, and AhR, and further analysis of interaction networks was performed." (PMID 34394108, 2021). "-The main cytokines involved in severe COVID-19 cases (IL-6 and TNF-α) are downstream of the TLR4 signaling pathway." (PMID 33981312, 2021). "The SARS-CoV-2 induced COVID-19 evoked overexpression of pro-inflammatory cytokines such as IL-6 and TNF-α, which are products of the TLR-4 pathway." (PMID 34200327, 2021). "In a clinical setting involving 48 subjects, the expression of TLR4 and its downstream signaling molecules as well as S100A9 (TLR4 ligand) were significantly upregulated in PBMCs from severe COVID-19 patients as compared to those from healthy controls." (PMID 34458281, 2021). "In addition, elevated levels of circulating TLR4 DAMPs in COVID-19 patients (beta-defensin-3; fibrinogen; heat-shock protein 70; HMGB1; syndecan; S100A8/9; and surfactant A and D) may be responsible for the feed-forward loop of the persistent inflammation, resulting in cytokine storm." (PMID 33498183, 2021). "Infrared light therapy has been shown to decrease TLR4-dependent induction of IL-6, IL-8, TNF-α, INF-α, and INF-β in COVID-19 hyperinflammation." (PMID 34835108, 2021). "Lung cells from COVID-19 patients show expression of HIF1α, TLR2, TLR4, PFKFB3, CXCR1, −2 and −4, SOD2, PLAUR and other genes expressed in immature myeloid cells." (PMID 33345622, 2021). "The difference between COVID-19 MILD and COVID-19 SEVERE TLR3 and TLR4 mRNA expression at admission widened during follow-up." (PMID 34315957, 2021). "NFKB1, NFKB2, IRF1, and CXCR3 were specifically up-regulated in COVID-19, and CXCL10, STAT1, TLR4, and genes for class II HLA and immunoproteasome subunits were specifically up-regulated in influenza." (PMID 32651212, 2020). "When we directly compared COVID-19 and influenza, NFKB1, NFKB2, and TNF were up-regulated in COVID-19, whereas STAT1, TLR4, and genes for immunoproteasome subunits were up-regulated in influenza." (PMID 32651212, 2020). "elucidated the link between COVID-19 and TLRs, revealing upregulation of TLR4-mediated inflammatory signaling molecules and identifying S100A9 as a potential biomarker, offering insights into targeting TLR4-mediated inflammation therapeutically." (PMID 40386784, 2025).